PTCH1 (patched 1)
Diseases named in the same sentence as PTCH1 in open-access papers (continued):
Sharing a sentence is not in itself a finding about the gene and the disease.
idiopathic pulmonary fibrosis (4 papers, 2013 to 2022). Idiopathic pulmonary fibrosis (IPF) is a nonneoplastic pulmonary disease that is characterized by the formation of scar tissue within the lungs in the absence of any known cause. "In idiopathic pulmonary fibrosis in human lungs, the increased expression of a lot of developmental pathway genes isexpressed by microarray data including Ptch1." (PMID 35681469, 2022). "Similarly, in Idiopathic pulmonary fibrosis, Shh ligand is expressed in bronchiolar and alveolar epithelial cells while Ptch1 and SMO have been observed in fibroblasts and mesenchymal cells forming fibroblast foci." (PMID 23667589, 2013). "Pulmonary fibrotic diseases such as idiopathic pulmonary fibrosis (IPF), interstitial lung disease, and usual and nonspecific interstitial pneumonia are all characterized by expression of Shh and Ptch1 in areas of fibrosis." (PMID 29214147, 2017).
metastatic disease (4 papers, 2004 to 2022). "Furthermore, four available metastatic tumors all have high expression of PTCH1 and HIP." (PMID 15482598, 2004). "In this cohort, the Kaplan–Meier analysis for a subset of patients with metastatic disease who did not receive immunotherapy indicated that a high level of Ptch1 in patient samples significantly correlated with a lower overall survival time." (PMID 32526884, 2020).
neuroblastoma (4 papers, 2016 to 2021). Neuroblastoma (NB) is the most common solid, extracranial childhood tumor. "We also found mutations in genes with no reported association to the diagnosis of the patient, such as BRCA1 and PTCH1 mutations in neuroblastoma, as well as PMS2 mutations in leukemia." (PMID 33674644, 2021). "Comparative cross species analysis of all 25 non-synonymous coding mutated genes detected in the mouse models resulted in three matches (DICER1, ZNF574 and PTCH1) in the list of 883 genes reported to harbor non-synonymous coding mutations in human neuroblastoma." (PMID 29492199, 2018). "A p.A300D missense mutation in the PTCH1 gene was previously reported in human neuroblastoma, suggesting that missense mutations could impair neuroblast differentiation and cooperate in MYCN driven tumor formation." (PMID 29492199, 2018).
ovarian tumors (4 papers, 2011 to 2023). "The Hh pathway-related proteins, including Ptch1 and Gli1 proteins, have been expressed in primary ovarian tumors and cell lines, furthermore, the abnormal activation of this pathway contributes to the malignancy of OC." (PMID 37851362, 2023). "In addition, we analyzed SHH, SMO, Ptch1, and Gli1 mRNA levels in the 4 individual patient samples we used to generate tumor xenografts for analyzing the effect of Hh pathway inhibition on ovarian tumor growth in vivo." (PMID 22140510, 2011). "Consistent with previous results, GLI1 and GLI3 (HH pathway transcriptional effectors), PTCH1 (HH signaling repressor and target gene), SMO (HH signaling activator), IHH and SHH (HH pathway ligands) were expressed in ovarian tumors, albeit at variable levels." (PMID 26755648, 2016).
renal fibrosis (4 papers, 2020 to 2024). A final common manifestation of a wide variety of chronic kidney diseases characterized by glomerulosclerosis and tubulointerstitial fibrosis. "In renal fibrosis, miR-342-5p has been revealed to target Ptch1 and inhibit its transcription factor FoxO3, leading to autophagy in the TGF-β1-stimulated TCMK-1 (mouse kidney) cells." (PMID 39379100, 2024). "The results showed that PTCH1 expression was regulated negatively by miR-342-5p and positively by FOXO3, PTCH1-induced autophagy in TCMK-1 cells stimulated by TGF-β1 was downregulated and renal fibrosis was ameliorated." (PMID 36105212, 2022).
rhabdomyoma (4 papers, 2012 to 2022). A benign mesenchymal tumor arising from skeletal or cardiac muscle. "Mutations in PTCH1 and SMO as well as homozygous deletions in PTCH1 were identified in three out of five human fetal rhabdomyoma samples." (PMID 36010600, 2022). "Two out the three “rhabdomyoma‐like” ERMS had PTCH1 deletion on CGH array, including one with unknown BANZ1‐FANCC fusion." (PMID 32087612, 2020). "In addition, a recent study found that 12 out of 34 fetal rhabdomyomas and eRMS lacked PTCH1 immunoreactivity and four of nine tumors examined had LOH at the PTCH1 locus." (PMID 22619564, 2012).
xeroderma pigmentosum (4 papers, 2011 to 2025). Xeroderma pigmentosum (XP) is a rare genodermatosis characterized by extreme sensitivity to ultraviolet (UV)-induced changes in the skin and eyes, and multiple skin cancers. "Furthermore, mutations occurring in the PTCH1 gene have been characterized in BCC patients with rare genetic disorders including xeroderma pigmentosum (XP) as well as in sporadic BCC." (PMID 34630850, 2021). "The distribution pattern of PTCH1 mutations has been analyzed in patients with NBCCS as well as in several tumors including BCCs, BCCs with xeroderma pigmentosum syndrome (XP-BCCs), and sporadic medulloblastomas." (PMID 24204797, 2013).
and Stomach Cancers (3 papers, 2013 to 2023). "Recently, in a mixed fibrous/myxoid type of gastric neoplasm called plexiform fibromyxoma, a link was established between Hedgehog signaling (Hh) and loss of PTCH1." (PMID 32964316, 2020). "In summary, SMO and/or PTCH1 mutations are present at low frequency in different histologic subtypes of gastric tumors and these do not appear to be driver mutations." (PMID 23349881, 2013).
astrocytoma (3 papers, 2009 to 2017). "Our observations on the expression of GLI1, Cyclin D2, and PTCH1 in astrocytoma cell lines as well as tumor samples revealed a significant proportion of samples showing low or null levels of Cyclin D2 and PTCH1, even in the presence of high GLI1 expression." (PMID 21059263, 2010). "NUSAP1 also upregulated the expression of the downstream targets of HH pathway including PTCH1, HIP1, CCND1, CCNE1 and HDAC1 in astrocytoma." (PMID 28899410, 2017). "On the contrary, we observed significant correlation of GLI1 expression with downstream target genes PTCH1 (p = 0.07), Cyclin D2 (p = 0.006), Plakoglobin (p = 0.02), PAX6 (p = 0.006) and NKX.2.2 (p = 0.0001) in astrocytoma cell lines." (PMID 21059263, 2010).
colon adenocarcinoma (3 papers, 2023 to 2024). "Based on the analysis of the different sample regions, it can be deduced that the PTCH1 protein is preferentially expressed in the stromal compartment of both sinonasal and referent colon adenocarcinoma." (PMID 38731849, 2024). "Mutations in PTCH1 were most prevalent in endometrial cancer (TCGA-UCEC), colon adenocarcinoma (TCGA-COAD) and stomach adenocarcinoma (TCGA-STAD)." (PMID 36672319, 2023).
craniosynostosis (3 papers, 2017 to 2021). Craniosynostosis is defined as the premature fusion of one or more cranial sutures leading to secondary distortion of skull shape resulting in skull deformities with a variable presentation. "Mutations in other HH pathway members such as Ptch1, Smo, Gli3, and Rab23 also cause craniosynostosis in humans and/or mice." (PMID 34880220, 2021). "An ENU-induced mouse model representing a hypomorphic allele of Ptch1 has bilateral craniosynostosis of the lambdoid suture, similar to Gli3Xt−J/Xt−J mice." (PMID 29311969, 2017). "Despite, Fuzzy null allele mice have increased repression of GLI3R they also exhibit craniosynostosis, all be it a different suture from that fused in Gli3Xt−J/Xt−J and Ptch1 mutant mice." (PMID 29311969, 2017). "Anyway, this finding may strengthen the importance of the role of the PTCH1, especially regarding the syndromic craniosynostosis." (PMID 31578813, 2020).
cyst (3 papers, 2013 to 2025). A sac-like closed membranous structure that may be empty or contain fluid or amorphous material. "Our findings highlight that OKC pathogenesis not only involves increased expression of cell cycle-promoting proteins (secondary to PTCH1 mutations and Hedgehog pathway activation), but also reveals a significant role for apoptosis regulation in the epithelial lining of the cyst." (PMID 40818142, 2025). "In the 2022 classification, OKC remains classified as a cyst; molecular studies have detected frequent mutations in the tumor suppressor gene PTCH1, a gene that activates the SHH pathway, leading to aberrant epithelial proliferation, sparking debates on whether OKC is a cyst or a cystic neoplasm." (PMID 38750607, 2024).
depression (3 papers, 2024 to 2025). "The Patched 1 (PTCH1) gene was associated (p = 1.80e-06) with variance in depression." (PMID 38746362, 2024).
developmental delay (3 papers, 2021 to 2023). "Herein, we report a novel de novo splice site mutation in the PTCH1 gene related to mild developmental delay and autistic traits in a 4-year-old male patient." (PMID 37752108, 2023). "Severe global developmental delay or developmental delay/cognitive deficits were documented in 3 patients; 2 of them carried PTCH1 mutations, 1 patient carried a SUFU variant." (PMID 34888241, 2021).
diabetes (3 papers, 2014 to 2023). "These included proteins expressed by pancreatic islet cells (Ptch1, Disp1, Pck1, and Cacna1e) as well as proteins known to be associated with diabetes mellitus susceptibility or glucose metabolism (Adcy8, Perm1, Sorbs1, and Pla2g6)." (PMID 37934865, 2023). "Ontological classification demonstrates that these 14 genes are associated with diabetes (ALMS1P; RAET1L; GYS1; RBM47; EFR3B), cancer (RPL27A; SPAM1; PTCH1; ZNF277; USP35; CDC86), or metabolism (C3orf15; AOC2; GOT1)." (PMID 24885560, 2014). "In this study, we confirmed that impairment of primary cilia induced by diabetes directly led to inhibition of Hedgehog signaling, characterized by reduced SHH/Gli2 expression and increased Ptch1/Sufu expression." (PMID 36552853, 2022).
ductal carcinomas in situ (3 papers, 2014 to 2019). "Additionally, there is evidence for loss of PTCH1 expression due to promoter methylation in human breast cancer, which correlated with decreased expression in samples from human ductal carcinomas in situ (DCIS) and in invasive ductal carcinomas." (PMID 25252859, 2014). "A decrease in PTCH1 expression was observed in ductal carcinomas in situ (DCIS) and invasive ductal carcinomas compared to mammary hyperplasia and normal breast tissue." (PMID 31027259, 2019).
endometrial cancer (3 papers, 2018 to 2023). Primary or metastatic malignant neoplasm involving the endometrium (mucous membrane that lines the endometrial cavity). "The pro-oncogenic role of Patched-1 and/or its association with the administered treatment merits functional validation and confirmation in larger series of endometrial cancer." (PMID 30521558, 2018). "Here, we report a 2.3–5.85 % prevalence of mutations in the PTCH1 CTD in the stomach, colorectal and endometrial cancers, with three frequent frameshift spots that result in truncation of the wild-type sequence after S1203, R1308 and Y1316." (PMID 36672319, 2023). "Overexpression of Patched-1 has been reported in uterine and endometrial carcinoma, while Gli1 siRNA has been shown to suppress the expression of Patched-1 and induce apoptosis in Huh7 cells." (PMID 30521558, 2018). "The upregulated hsa-mir-200a-b is associated with the decreased expression of the PTCH1, CCND2, PDGFRA, FOSB and ABL1 genes in endometrial cancer tissue while hsa-mir-429 is correlated with the decreased expression of the ALDH1A1 gene, besides some antibodies, PROTACs and inhibitory molecules." (PMID 36704357, 2022).
Fanconi anemia (3 papers, 2016 to 2024). Fanconi anemia (FA) is a hereditary DNA repair disorder characterized by progressive pancytopenia with bone marrow failure, variable congenital malformations and predisposition to develop hematological or solid tumors. "Tumor 2 had bi-allelic chromosome 9q deletions of PTCH1 and FANCC (Fanconi anemia complementation group C)." (PMID 31362756, 2019).
Intellectual disability (3 papers, 2020 to 2021). "In addition, mutations in PTCHD1, a gene encoding a protein that displays secondary structures similar to Ptch1, are found in patients with intellectual disability and ASD." (PMID 32989040, 2020). "For example, for 9q22, some deletions (not all involving PTCH1) associated with language delay or intellectual disability are of paternal origin, suggesting that the paternal allele is expressed in that region." (PMID 32635940, 2020).
lung adenocarcinoma (3 papers, 2016 to 2023). A carcinoma that arises from the lung and is characterized by the presence of malignant glandular epithelial cells. "CTC counts correlated to tumor progression in patients with early lung adenocarcinoma and successfully detected typical mutant genes (Notch1, IGF2, EGFR, and PTCH1) and genes in smokers as predictive biomarkers." (PMID 37371825, 2023). "Three genes, PTCH1, CTNNB1, and FYN, have been predicted to contribute to the initiation and progression of lung adenocarcinoma in all the six gene sets." (PMID 27412431, 2016).
metastatic cancers (3 papers, 2018 to 2021). A carcinoma which has spread from the original site of growth to another anatomic site. "Another interesting candidate for follow-up studies was the tumor suppressor Patched 1 (PTCH1), a multi-pass transmembrane protein which is over-expressed in many metastatic cancers." (PMID 33845897, 2021). "Recent studies showed that the Hedgehog receptor Ptch1, which is over-expressed in many recurrent and metastatic cancers, is a multidrug transporter and it contributes to the efflux of chemotherapeutic agents such as doxorubicin, and to chemotherapy resistance." (PMID 30110910, 2018).
odontogenic tumor (3 papers, 2015 to 2025). "Furthermore, the potential of SMO and PTCH1 mutations to guide the treatment of selected odontogenic tumours warrants further investigation." (PMID 41364259, 2025).
skin basal cell carcinoma (3 papers, 2016 to 2023). The most frequently seen skin cancer. "In a previous study, PTCH1-driven skin basal cell carcinoma showed a high level of TMB, thus, the TMB levels in the PTCH1 mutation and wild-type groups from our cohort and database were evaluated." (PMID 34028566, 2022). "In support of our findings there are reports of PTCH1 also acting as an oncogene in a mouse model of skin basal cell carcinomas." (PMID 26768750, 2016). "It is important to mention that the most common cancer type with loss of function mutations of PTCH1 is basal cell carcinoma of the skin (80–90%), which is not registered in the Cancer Genome Atlas." (PMID 36672319, 2023).
squamous cell carcinoma (3 papers, 2016 to 2023). A carcinoma arising from squamous epithelial cells. "A different type of PTCH1 mutation in its cytosolic C-terminal domain (CTD) has been reported in squamous cell carcinomas of the skin and upper GI tract." (PMID 36672319, 2023).
Alzheimer disease (2 papers, 2021 to 2024). A progressive, neurodegenerative disease characterized by loss of function and death of nerve cells in several areas of the brain leading to loss of cognitive function such as memory and language. "We also found distinct variants (high PP.H3) in KAT8 with FVC for Alzheimer’s disease (from GWAS meta-analysis), in PTCH1 with FVC and FEV1/FVC for fluid intelligence and reaction time and in SERPINC1 with FVC for reaction time." (PMID 39544701, 2024). "We also found distinct variants associated with lung function and cognitive function in KAT8 (forced vital capacity and Alzheimer’s disease) and PTCH1 (forced vital capacity and forced expiratory volume in 1 s to forced vital capacity ratio with fluid intelligence and reaction time)." (PMID 39544701, 2024). "On the other hand, a massive shortfall in PTCH1 and GLI1 was observed in the hippocampus of aged Alzheimer disease transgenic mice that would compromise the ability of genesis in both NSC and glial precursor cells." (PMID 34830484, 2021).
cataract (2 papers, 2021 to 2022). Partial or complete opacity of the crystalline lens of one or both eyes that decreases visual acuity and eventually results in blindness. "Mice heterozygous for Ptch1 develop spontaneous cataracts and are highly susceptible to cataract induction by exposure to ionizing radiation at an early postnatal age, when lens epithelial cells undergo rapid expansion in the lens epithelium." (PMID 35749127, 2022).
chordoma (2 papers, 2019 to 2021). Chordomas are rare malignant tumors arising from embryonic remnants of the notochord in axial skeleton. "Cranial chordomas were examined for the expression of Ptch1 and GLI1 by in situ hybridization." (PMID 30769952, 2019). "Suppression of the binding of the ligand Shh to PTCH1 by 5E1, robotnikinin or RU-SKI 43 could potentially stop tumor progression in our investigated chordomas." (PMID 30769952, 2019). "On the other hand, negative responses for PTCH1 and GLI1 were detected in the first spinal chordoma recurrences." (PMID 30769952, 2019).
ciliopathies (2 papers, 2018 to 2021). "Moreover, our genetic results reveal that inhibition of PTCH1 can prevent ciliopathy-associated midface defects." (PMID 34672258, 2021). "Thus, reducing Ptch1 gene dosage rescues midface expansion in both models of ciliopathy-associated hypoplasia." (PMID 34672258, 2021). "In summary, our findings demonstrate that non-canonical Hh signaling mediated by events proximal to PTCH1 and SMO occur independently of primary cilia and, therefore, might be of relevance in cancer and ciliopathies." (PMID 30148884, 2018).
cleft lip (2 papers, 2024). Congenital defect in the upper lip where the maxillary prominence fails to merge with the merged medial nasal prominences. "Eight significant variants associated with craniofacial malformations such as non-syndromic cleft lip and palate, mandibular prognathism, ocular abnormalities, and tooth defects are found in AXIN2, BMP2, BMP4, NOTCH3, PTCH1, SOX10, and WNT10A." (PMID 38785976, 2024).
colitis (2 papers, 2016 to 2022). Inflammation of the colon. "The loss of one Ptch1 allele had a marked effect on tumour development, yet it did not detectably influence the course of the DSS-induced colitis." (PMID 27492255, 2016). "Notably, our data show that induction of experimental colitis by DSS does not modify the rate of MB development in Ptch1+/− mice." (PMID 36232813, 2022).
colorectal tumors (2 papers, 2013 to 2017). "PTCH1 mutations that coded nonsynonymous amino acid changes were found in 4 percent (12/296) of the colorectal tumors that have been comprehensively profiled and curated." (PMID 24368541, 2013).
embryonal rhabdomyosarcoma (2 papers, 2019 to 2025). A poorly circumscribed morphologic variant of rhabdomyosarcoma. "Approximately a third of embryonal rhabdomyosarcomas have a loss of chromosome region 9q22 including the PTCH1 locus, leading to constitutive Hh pathway activation." (PMID 40983796, 2025).
emphysema (2 papers, 2019 to 2024). "Indeed, previous studies showed that lung cells from human COPD/emphysema patients exhibited Hh hyperactivation with upregulated GLI1 and PTCH1, compared with those from non-COPD/emphysema controls." (PMID 31323955, 2019).
head and neck carcinoma (2 papers, 2017 to 2020). A carcinoma that arises from the head and neck region. "Few studies investigated the epigenetic regulation of Shh signaling in head and neck carcinomas; thus, we aimed to assess whether known negative regulators of this pathway (HHIP, PTCH1, SUFU, ZIC1, ZIC4) undergo methylation in HNSCC." (PMID 27553089, 2017).